AIM2 (absent in melanoma 2)
Diseases named in the same sentence as AIM2 in open-access papers (continued):
Sharing a sentence is not in itself a finding about the gene and the disease.
renal carcinoma (continued). "Taken together, these results indicated that Ad‐CAIXpromotor‐AIM2 could efficiently enhance the oncolytic effect by inhibiting renal cancer cell proliferation and increasing cell apoptosis." (PMID 32725966, 2020). "Similarly, Ad‐CAIXpromotor‐AIM2 remarkably enhanced the inhibition of cell proliferation and migration and promoted cell apoptosis in infected renal cancer cells." (PMID 32725966, 2020). "Furthermore, overexpression of AIM2 in human renal cancer suppressed cell metastasis via enhancing autophagy induction." (PMID 32725966, 2020). "Of note, AIM2 as a tumour suppressor is a prognostic marker and an independent predictor of disease progression in renal cell cancer, and is also used as the therapy target for renal cancer therapy." (PMID 32725966, 2020). "Furthermore, lung metastasis of renal cancer mice was also suppressed by Ad‐CAIXpromotor‐AIM2 treatment accompanied by the decreased tumour fossil in lung tissues." (PMID 32725966, 2020). "The infection of Ad‐CAIXpromotor‐AIM2 at a MOI of 10 also killed the renal cancer cells." (PMID 32725966, 2020). "Taken together, these data indicated that Ad‐CAIXpromotor‐AIM2 treatment with low toxicity could effectively prevent the aggravation of tumour in renal cancer model." (PMID 32725966, 2020). "Our results showed Ad‐CAIXpromotor‐AIM2 treatment could increase oncolytic efficiency in renal cancer cells and exert the anti‐tumour effect in primary solid or metastasis tumour." (PMID 32725966, 2020). "To assess whether Ad‐CAIXpromotor‐AIM2 could also protect mice from tumour metastasis, we established a murine lung metastasis model of renal cancer." (PMID 32725966, 2020). "The CAIXpromotor‐AIM2 adenoviruses (Ad‐CAIXpromotor‐AIM2) could efficiently express E1A and AIM2 in renal cancer cells." (PMID 32725966, 2020). "AIM2 as a tumour suppressor could inhibit the malignant behaviour of renal cancer cells, implied that AIM2 is a potent target gene for renal cell carcinoma therapy." (PMID 32725966, 2020). "Therefore, we developed the Ad‐CAIXpromotor‐AIM2 that was an E1B55kD deletion with the E1A gene controlled by CAIXpromotor, armed with the AIM2 gene to enhance the therapeutic efficacy of renal cancer." (PMID 32725966, 2020). "In addition, elevating AIM2 expression by delivering an exogenous AIM2 promotor can significantly inhibit the proliferation and invasion of renal carcinoma." (PMID 31242947, 2019). "Moreover, the colony formation assay showed that H1/AIM2 significantly decreased capabilities of colony formation in renal cancer cells compared with control." (PMID 30160343, 2018). "Delivery of H1/pAIM2 in renal carcinoma cells could remarkably increase the expression of AIM2, and subsequently decrease cell proliferation, migration, and invasion as well as enhance cell apoptosis." (PMID 30160343, 2018). "Then, we further investigated the function of AIM2 in the proliferation of renal cancer cells." (PMID 30160343, 2018). "In this study, we observed that AIM2 expression was significantly decreased in RCC specimen and renal carcinoma cell lines, indicated that AIM2 might be served as a therapeutic target for RCC treatment." (PMID 30160343, 2018). "We next investigated the role of H1/AIM2 in migration and invasion of renal cancer cells." (PMID 30160343, 2018). "Meanwhile, we detected the expression of AIM2 in renal cancer cell lines." (PMID 30160343, 2018). "Thus, AIM2 might be applied as a therapeutic gene to enhance the potential efficacy of CARd for renal cancer treatment." (PMID 32725966, 2020). "The MFI analysis showed that a significant increasing expression of AIM2 was observed in Ad‐AIM2 or Ad‐CAIXpromotor‐AIM2‐infected cells compared with the control cells, and indicated AIM2 gene was successfully expressed in Ad‐AIM2 or Ad‐CAIXpromotor‐AIM2‐infected renal cancer cells." (PMID 32725966, 2020).
renal carcinoma (continued). "Accordingly, E1A protein confirmed by the MFI also could be efficiently expressed in Ad‐CAIXpromotor or Ad‐CAIXpromotor‐AIM2‐infected renal cancer cells, and indicated Ad‐CAIXpromotor or Ad‐CAIXpromotor‐AIM2 efficiently droved the E1A expression in CAIX antigen‐positive cells." (PMID 32725966, 2020). "In this study, our results suggested that H1/AIM2 nanoparticles could inhibit malignancies of renal cancer through enhancing the inflammasome pathway, which suggested an effective treatment of H1/AIM2 against renal cancer." (PMID 30160343, 2018). "Therefore, it indicated that therapeutic strategy by H1/AIM2 might provide a new way for manipulating renal cancer." (PMID 30160343, 2018). "Furthermore, we also detected the local expression of AIM2 in renal cancer cells." (PMID 30160343, 2018). "In renal carcinoma cell lines, 786-O and OSRC-2, tumor cell-derived AIM2 inhibits cell migration and invasion by enhancing autophagy." (PMID 36932407, 2023). "Here, we found that AIM2 expression was significantly decreased in RCC patient specimens and renal carcinoma cell lines (786‐O and OSRC‐2)." (PMID 30160343, 2018). "Recent studies have identified the Absent in Melanoma 2 (AIM2) inflammasome as a novel biomarker for renal cancer, promoting cancer progression and contributing to sunitinib resistance." (PMID 39335103, 2024).
Autoimmunity (14 papers, 2011 to 2025). The occurrence of an immune reaction against the organism's own cells or tissues. "As we show here for Aim2 knockout mice, it will be important to characterize the locus in different mouse strains when determining genetic susceptibility to pathogen infection, inflammation, and autoimmunity." (PMID 28679751, 2017). "AIM2 is a host protein and vaccination with pAIM2 might have autoimmunity risk." (PMID 28642849, 2017). "To date, the role of inflammasomes in autoimmunity have largely focused on NLRP3 and AIM2, but other inflammasome molecules such as NLRP1, and NLR family CARD domain-containing protein 4 (NLRC4) have also been implicated in autoimmunity." (PMID 37081890, 2023). "The primary function of AIM2 in myeloid cells is activation in response to stimulation by foreign dsDNA, whereas AIM2 is highly expressed and is required to suppress autoimmunity in regulatory T cells." (PMID 37515138, 2023). "Inefficient clearance of cellular debris in SLE results in the elevation of reactive oxygen species and mediates NLRP3 activation, and the accumulation of cytosolic self-DNA in autoimmunity triggers AIM2 inflammasome-mediated IL-1β production." (PMID 28266599, 2017). "AIM2 inflammasome is gaining increasing recognition for its role in autoimmunity." (PMID 41369412, 2025). "Immune system diseases further amplify cardiovascular injury: population-level data link autoimmunity to heightened CVD risk, while AIM2- and NLRP3-dependent axes accelerate atherogenesis and destabilize plaques, particularly in clonal hematopoiesis and after acute infectious or ischemic insults." (PMID 41488670, 2025). "Studies demonstrate that AIM2 displays a number of alternative functions independent of inflammasome activation in various cell types, that affect the progression of autoimmunity." (PMID 37081890, 2023).
gastric cancer (14 papers, 2020 to 2024). A primary or metastatic malignant neoplasm involving the stomach. "In some cancers, AIM2 was considered as the tumor suppressor, because it was discovered inactivated and mutated in these cancers, for instance, colorectal and gastric cancers." (PMID 36276158, 2022). "For instance, in gastric cancer (GC), overexpression of AIM2 had been associated with an increased tumor burden in xenografts derived from human GC cell lines." (PMID 39600708, 2024). "F For instance, AIM2 knockdown inhibits the proliferation, migration, and enlargement of gastric cancer cells, thereby decelerating tumor progression." (PMID 37932362, 2023). "In gastric cancer, the upregulation of AIM2 expression has been confirmed to promote tumorigenesis in mouse models, while target blocking AIM2 can inhibit tumor occurrence." (PMID 35846123, 2022). "The proliferation, migration, and invasion of stomach cancer cells are inhibited by CCL19 via the CCL19/CCR7/AIM2 pathway." (PMID 34367971, 2021). "For example, CCL19 inhibited cell proliferation, migration, and invasion in gastric cancer by activating the CCR7/AIM2 signaling pathway, which could be a potential therapeutic approach." (PMID 33344235, 2020). "Therefore, CCL19 can activate the CCR7/AIM2 signaling pathway, suggesting that it could be a potential therapeutic method to treating gastric cancer." (PMID 36248785, 2022). "CCL19 overexpression significantly inhibited gastric cancer cell proliferation and tumor growth through CCL19/CCR7/AIM2 pathway." (PMID 34544443, 2021). "The innate immune cytosolic DNA sensor absent in melanoma 2 (AIM2) contributes to the pathogenesis of numerous autoimmune and chronic inflammatory diseases, as well as cancers including gastric cancer." (PMID 36967659, 2023). "Similarly, AIM2 could mitigate tumor growth and metastatic progression by inhibiting the PI3K/Akt/mTOR pathway in gastric cancer and osteosarcoma." (PMID 38166970, 2024).
lung fibrosis (13 papers, 2019 to 2025). "In sharp contrast, PC patients with signs of lung fibrosis were susceptible to AIM2 triggering of TGF-β release (p=0.0168)." (PMID 35844548, 2022). "The microbial burden was however associated with baseline IL-1β release as well as AIM2 and IL-18 mRNA expression in lung fibrosis." (PMID 34220810, 2021). "We also found that the deficiency of GLUT1 suppressed the activation of AIM2 inflammasome in lung tissues under S. pneumoniae-mediated exacerbation of lung fibrosis." (PMID 32121297, 2020). "AIM2 inflammasome was recently linked to the pathogenesis of lung fibrosis and progression." (PMID 34220810, 2021). "This receptor mediates the release of pro-inflammatory and pro-fibrotic factors involved in PC-associated lung fibrosis, suggesting that AIM2 is an attractive molecular target that could help to early identify PC patients who are more likely to develop lung fibrosis and improve screening strategies." (PMID 35844548, 2022). "Emerging evidence has indicated that activation of the AIM2 inflammasome triggers TGF-β release in an IL-1α-dependent manner in peripheral blood mononuclear cells from patients with idiopathic pulmonary fibrosis." (PMID 39870644, 2025). "In contrast, PBMCs from PC patients who exhibited lung fibrosis markers displayed heightened AIM2 activation, leading to the release of IL-1α, IFN-α, and TGF-β." (PMID 40072090, 2025). "According to our results, we found that the AIM2 inflammasome-dependent pathway was involved in the release of IFN-α from PC patients with signs of lung fibrosis." (PMID 35844548, 2022). "Blocking the AIM2 inflammasome aids in reducing lung fibrosis and inflammation brought on by radiation." (PMID 36110858, 2022). "Together these data provide strong evidence that AIM2 inflammasome activation induces IL-1α release from circulating immune cells of PC patients with signs of lung fibrosis, implying systemic inflammation." (PMID 35844548, 2022). "In this context, we found that both CD14+ and CD14+HLA-DR+ PBMCs from PC patients with signs of lung fibrosis expressed higher levels of AIM2 and confirmed the release of IL-1α and TGF-β after its triggering." (PMID 35844548, 2022). "In contrast, AIM2 stimulation in PBMCs from patients who presented lung fibrosis-like changes significantly increased (p=0.01) IL-1α levels (ctr: 34.75 ± 5.42 pg/ml vs PolydA:dT: 81.6 ± 16.5 pg/ml)." (PMID 35844548, 2022). "The pathophysiology of pulmonary fibrosis involves mitochondrial oxidation-driven overactivation of the AIM2 inflammasome via the production of IL-1α, IFN-α, and TGF-β." (PMID 36110858, 2022). "In sharp contrast, PBMCs from PC patients with signs of lung fibrosis were highly responsive to AIM2 activation, which induced the release of IL-1α, IFN-α and TGF-β." (PMID 35844548, 2022). "In this study we provide evidence of an implication of NLRP3 and AIM2 inflammasome in patients with lung fibrosis." (PMID 34220810, 2021). "Of note, streptococcal infection leads to acute exacerbation of lung fibrosis in mice through AIM2 inflammasome activation while inflammasome activation was dysregulated in BAL cells from ILD patients." (PMID 34220810, 2021). "Of particular interest, GLUT-1 dependent glycolysis promotes exacerbation of lung fibrosis during S. pneumoniae infection via AIM2 activation and several studies have suggested a relative abundance of Streptococcus genera in IPF." (PMID 34220810, 2021). "Recently, we have described that glucose transport 1 (GLUT1)-dependent glycolysis regulates the exacerbation of lung fibrosis via AIM2 inflammasome activation." (PMID 32121297, 2020). "Recently, our findings demonstrated that the expression and activation of AIM2 inflammasome expression and activation is enhanced in a lung fibrosis exacerbation model." (PMID 32121297, 2020). "We also found that DROSHA and AIM2 protein expression were increased in alveolar macrophages of lung tissues in a mouse model of bleomycin-induced pulmonary fibrosis." (PMID 31434287, 2019).
lung fibrosis (continued). "Although not yet fully completed, our study provides the role of DROSHA in AIM2 inflammasome-dependent lung inflammation in the pathogenesis of pulmonary fibrosis." (PMID 31434287, 2019). "Here we demonstrate that DROSHA contributes to AIM2 inflammasome activation-dependent lung inflammation during idiopathic pulmonary fibrosis." (PMID 31434287, 2019). "Here, we demonstrate that DROSHA regulates the absent in melanoma 2 (AIM2) inflammasome activation during idiopathic pulmonary fibrosis (IPF)." (PMID 31434287, 2019). "Our findings suggest DROSHA-dependent AIM2 inflammasome activation contributes to pulmonary fibrosis." (PMID 31434287, 2019). "The pro-inflammatory cytokines IL-1β and IL-18 were elevated in PBMCs of IPF patients and mice with BLM-induced pulmonary fibrosis, with this increase linked to the release of the pro-fibrotic cytokine TGF-β through an AIM2 canonical inflammasome-dependent pathway." (PMID 39795884, 2024). "Notably, IL-1α release was observed in 18 out of 24 PC patients with lung fibrosis-like changes (75%) after AIM2 activation." (PMID 35844548, 2022). "The goal of this study was to understand the involvement of the Absent in melanoma-2 (AIM2) inflammasome in PC-associated lung fibrosis-like changes revealed by chest CT scans." (PMID 35844548, 2022). "Moreover, the responsiveness of AIM2 correlated with higher expression of the receptor in circulating CD14+ cells in PBMCs from patients with signs of lung fibrosis." (PMID 35844548, 2022). "Therefore, recent studies suggest that the activation of NLRP3 or AIM2 inflammasome-dependent inflammation has a critical role in the progression of lung fibrosis." (PMID 32121297, 2020). "In this study we demonstrated that AMs in pulmonary fibrosis secrete abundantly IL-1β following stimulation of the NLRP3 and AIM2 inflammasomes compared to healthy subjects." (PMID 34220810, 2021). "Since DROSHA and AIM2 expression levels were elevated in alveolar macrophages during lung fibrosis, we next investigated the function of DROSHA during AIM2 inflammasome activation in alveolar macrophages." (PMID 31434287, 2019). "Here, we show that both DROSHA and AIM2 protein expression are significantly elevated in alveolar macrophages of patients with IPF and a mouse model of bleomycin-induced pulmonary fibrosis." (PMID 31434287, 2019). "Peripheral blood mononuclear cells (PBMCs) derived from PC patients without signs of lung fibrosis showed no AIM2 activation." (PMID 40072090, 2025). "In contrast, AIM2 expression on circulating CD14+ PBMCs from PC patients without signs of lung fibrosis had much lower expression of AIM2 and lower levels of cytokine release." (PMID 35844548, 2022). "Thus, we consider that AIM2 activation that leads to IL-1α, IFN-α and TGF-β release is likely to be involved in the establishment of lung fibrosis in PC syndrome." (PMID 35844548, 2022). "Peripheral blood mononuclear cells (PBMCs) obtained from PC patients who did not develop signs of lung fibrosis were not responsive to AIM2 activation by Poly dA:dT." (PMID 35844548, 2022). "While the study of the NLRP3 inflammasome has been explored in various lung fibrosis models, the role of AIM2 inflammasome has not been fully investigated." (PMID 32121297, 2020). "While the upstream regulation of NLRP3 inflammasome activation has been well described in lung fibrosis models, the mechanism by which AIM2 inflammasome is activated in lung fibrosis has not been fully elucidated." (PMID 32121297, 2020). "In our previous studies, we showed that absent in melanoma 2 (AIM2) inflammasome, a multimeric protein complex, was responsible for the release of IL-1α and TGF-β by peripheral blood mononuclear cells (PBMCs) of idiopathic pulmonary fibrosis (IPF) patients." (PMID 35844548, 2022). "However, it should be noted that not all PC patient-derived PBMCs with signs of lung fibrosis had increased TGF-β (12/26, 46% of patients) after AIM2 stimulation." (PMID 35844548, 2022).
Obesity (13 papers, 2019 to 2025). Accumulation of substantial excess body fat. "Studies have shown that mice deficient in AIM2 develop spontaneous obesity and exhibit impaired glucose homeostasis, enhanced adipogenesis, and inflammatory responses, indicating that AIM2 prevents metabolic syndrome." (PMID 39158380, 2025). "In obesity, AIM2 appears to suppress adipogenesis and preserve glucose homeostasis independently of its inflammasome activity." (PMID 39158380, 2025). "The levels of caspase‐1 activity in adipose tissue or circulating IL‐1β are similar in obese WT and Aim2−/− mice, suggesting that AIM2 prevents obesity independently of its inflammasome activity." (PMID 39158380, 2025). "By contrast, in an animal experiment, AIM2-/- mice were more prone to obesity, impaired brown fat function, increased fasting blood glucose and insulin levels, and impaired metabolic functions such as IR when compared to WT mice." (PMID 36993972, 2023). "Correspondingly, a recent study showed an inflammasome-independent role of AIM2 in obesity and insulin resistance that is mediated by the up-regulation of Ifi202b and antiviral IFN signaling." (PMID 33710283, 2021). "Whether AIM2 also plays a role in LncRNA29RIK-mediated sensitivity to obesity needs to be further investigated." (PMID 40356927, 2025). "AIM2 has multifaceted roles in metabolic disorders such as obesity and diabetes." (PMID 39158380, 2025). "AIM2 variants have not been reported to cause obesity yet, and in our study, a frameshift variant of AIM2 was found in 4 patients who had a family history of obesity." (PMID 38469147, 2024). "Then, we selected 5 variants in genes previously reported to be associated with obesity, adipogenesis or linked to obesity-associated traits by genome-wide association studies (SLC25A5, AIM2, SNX16, CAMKK2 and PDE11A) for further analysis to identify candidate MOVs." (PMID 38469147, 2024). "However, the in vivo role of AIM-2 in obesity remains controversial." (PMID 33574823, 2020). "In this review, we summarize the current knowledge on the roles of TLR9, cGAS‐STING, AIM2, IFI16, DNA‐PK, and DDX41 in obesity, diabetes, fatty liver disease, and cardiovascular disease." (PMID 39158380, 2025). "In stark contrast to AIM2, ablation of key components of the inflammasome, such as NLRP1, NLRP3, ASC, caspase‐1, and IL‐1β, protects mice from HFD‐induced obesity and insulin resistance." (PMID 39158380, 2025). "There have been reports indicating that a lack of AIM2 can lead to obesity and insulin resistance through the upregulation of the Ifi202b pathway." (PMID 38429284, 2024).